TMEM97 (transmembrane protein 97)
Description:
Sigma-2 receptor implicated in the regulation of multiple cellular processes, including cholesterol biosynthesis and trafficking, membrane trafficking, autophagy, lipid membrane-associated protein trafficking, and stabilization of receptors at the cell surface, thereby contributing to the maintenance of cellular homeostasis. Reduces the availability of the lysosomal sterol transporter NPC1, likely through direct interaction, thereby regulating lipid transport, including cholesterol and LBPA, outside of late endosome/lysosome. Binds the regio- and stereoselective oxysterol 20(S)-hydroxycholesterol (20(S)-OHC). Ligand binding enhances association with NPC1 and modulates TMEM97-containing protein complexes involving PGRMC1 and TSPO, consistent with a role in cholesterol homeostasis. Also able to bind cholesterol (By similarity). Interacts with the salivary peptide histatin 1 (Hst 1/HTN1) at the ER membrane, which is critical for increasing mitochondria-ER contacts and stimulating Hst 1 wound healing properties. May alter the activity of some cytochrome P450 proteins. Although sharing homology with sterol isomerases through the EXPERA domain, lacks sterol isomerase activity; instead, may function as a sterol or oxysterol sensor. Acts as an ER quality control factor by promoting proteolytic degradation of nonproductive and extramitochondrial precursor proteins in the ER membrane, thereby removing them from the ER surface (By similarity).
Synonyms: S2R; MAC30; σ2R; sigma2R
Tractability: Small molecule: a high-quality ligand is known. Antibody: its Gene Ontology location is reachable by antibodies, with high confidence; UniProt predicts a signal peptide or a membrane-spanning region. PROTAC: ubiquitination databases record sites on it; its protein half-life has been measured; a small molecule that binds it is known.
Target class: Membrane receptor
Chemical probes: WLB-89462 (high quality)
Gene: Protein-coding gene on chromosome 17 (28,319,200 to 28,328,685, forward strand). Ensembl gene ENSG00000109084.
Subcellular location: Rough endoplasmic reticulum membrane; Nucleus membrane
Subcellular location (Human Protein Atlas): Endoplasmic reticulum
Gene Ontology:
Molecular function: protein binding; cholesterol binding; oxysterol binding
Biological process: cholesterol homeostasis; positive regulation of lipoprotein transport; positive regulation of wound healing; regulation of intracellular cholesterol transport; regulation of intracellular lipid transport; regulation of cell growth
Cellular component: endoplasmic reticulum; lysosome; nuclear membrane; plasma membrane; rough endoplasmic reticulum; rough endoplasmic reticulum membrane
Genetic constraint (gnomAD): Loss-of-function variants: 13 observed, 19.09 expected, observed/expected ratio (o/e) 0.68, 90% interval 0.44 to 1.08. The upper end of that interval is the gene's LOEUF score, 1.08, which puts it in group 4 of 6, group 1 being the genes least tolerant of losing a copy. Missense variants: 205 observed, 217.6 expected, observed/expected ratio (o/e) 0.94, 90% interval 0.84 to 1.06. Synonymous variants: 76 observed, 88.11 expected, observed/expected ratio (o/e) 0.86, 90% interval 0.72 to 1.04.
Homologues: Orthologues: macaque TMEM97 (98% identical), chimpanzee TMEM97 (93% identical), mouse Tmem97 (82% identical), rat Tmem97 (81% identical), pig TMEM97 (78% identical), rabbit TMEM97 (77% identical), guinea pig TMEM97 (74% identical), dog TMEM97 (69% identical), zebrafish tmem97 (57% identical), tropical clawed frog tmem97 (55% identical).
Diseases named in the same sentence as TMEM97 in open-access papers:
TMEM97 is named in the same sentence as 78 diseases in open-access papers, as found by Europe PMC text mining. Sharing a sentence is not in itself a finding about the gene and the disease. The quoted sentences say what the papers report.
Alzheimer disease (24 papers, 2019 to 2026). A progressive, neurodegenerative disease characterized by loss of function and death of nerve cells in several areas of the brain leading to loss of cognitive function such as memory and language. "Consistent with a role of S2R in synapses and in Alzheimer’s disease, S2R (TMEM97) has been demonstrated using Förster resonance energy transfer to colocalize with amyloid-β in synaptic densities." (PMID 37047224, 2023). "Recent studies in animal models of Alzheimer's disease and traumatic brain injury demonstrate that small molecules binding selectively to σ2R/TMEM97 are neuroprotective, suggesting that σ2R/TMEM97 is involved in pathways relevant to neurodegeneration." (PMID 36456686, 2022). "A further understanding of how TMEM97 may be regulated by different mediators and disease-relevant stressors is needed; however, in the case of Alzheimer’s disease, at least two reports suggest that TMEM97 is upregulated in synapses." (PMID 37047224, 2023).
breast cancer (21 papers, 2010 to 2025). A primary or metastatic malignant neoplasm involving the breast. "Upregulation of transmembrane protein 97 (TMEM97) has been associated with progression and poor outcome in multiple human cancers, including breast cancer." (PMID 34615853, 2021). "TMEM97 deficiency also suppressed cell viability, proliferation, colony formation, migration, invasion, and stemness properties in breast cancer cells." (PMID 34615853, 2021). "Previous studies have revealed that TMEM97 is highly expressed in breast cancer, and associated with disease progression and poor prognosis." (PMID 34615853, 2021). "High expression of TMEM97 was significantly associated with tumor progression, recurrence, and poor survival in breast cancer." (PMID 34615853, 2021). "TMEM97-mediated Wnt signaling is implicated in the tumorigenesis of breast cancer, and its targeted inhibition may be a promising therapeutic strategy for breast cancer." (PMID 34615853, 2021). "Furthermore, we demonstrate that PGRMC1 and TMEM97 expression are associated with an increased risk of tumor recurrence within the first 5 years following breast cancer diagnosis, in a manner that seems to be mediated by their association with cellular proliferation." (PMID 39804138, 2025). "Although we have demonstrated that PGRMC1 and σ2R/TMEM97 are involved in the same biochemical pathways within the cell, little is known about the impact of the individual components on breast cancer clinical outcomes." (PMID 39804138, 2025). "σ2R/TMEM97 is overexpressed in various cancers, including epithelial, lung, colorectal, ovarian, and breast cancers, and its overexpression has been linked to poor prognosis and metastasis in some of these cancers." (PMID 41008535, 2025). "Additionally, the association of σ2R/TMEM97 with proliferation indicates that the σ2R-selective in vivo radioligand imaging agent 18F-ISO-1 may be a useful marker for breast cancer imaging that could have utility in targeted cell-cycle therapy selection and evaluating response to therapy." (PMID 39804138, 2025). "σ2R/TMEM97 knockout in breast cancer cells downregulated the Wnt/β-catenin signaling pathway via LRP6 phosphorylation, suppressing tumor growth." (PMID 41008535, 2025). "In breast cancer, σ2R/TMEM97 is involved in the activation of the Wnt/β-catenin pathway that regulates cell growth, differentiation, and development." (PMID 41008535, 2025). "We also demonstrated in a subsequent clinical trial that in vivo quantification of a radioligand targeting TMEM97 correlates with proliferation in ER+ breast cancer." (PMID 39804138, 2025). "In our recent study, we showed that transmembrane protein 97 (TMEM97) promoted Wnt/β-catenin signaling by potentiating the association between LRP6 and CK1δ/ε, which is implicated in the tumorigenesis of breast cancer." (PMID 38183076, 2024). "Herein, we report that the TMEM97/σ2 receptor modulates the growth of ER-positive breast cancer cells via regulating ERα activities." (PMID 38067394, 2023). "In conclusion, the TMEM97/σ2 receptor has been identified as a novel regulator of ERα in breast cancer cell growth and responses toward tamoxifen." (PMID 38067394, 2023). "The bioinformatics data suggest that the survival of breast cancer patients is impacted by the TMEM97 mRNA level, especially for ER-positive patients." (PMID 38067394, 2023). "The clinical relevance of the TMEM97/σ2 receptor in breast cancer is at first indicated by the in silico analyses of a pubic database." (PMID 38067394, 2023).
breast cancer (continued). "In our study, we demonstrated that the overexpression of TMEM97 in breast cancer cells contributed to resistance to tamoxifen treatment, and the overexpressed cells continuously activated the mTOR/S6K1 signaling pathway and the ERα activity." (PMID 38067394, 2023). "In this study, we have made the following observations regarding the TMEM97/σ2 receptor in breast cancer." (PMID 38067394, 2023). "The results suggest an important role for TMEM97 in estrogen receptor activation and resistance to tamoxifen in breast cancer cells." (PMID 38067394, 2023). "Thirdly, the TMEM97/σ2 receptor regulates the ERα activities in the breast cancer MCF7 and T47D cells." (PMID 38067394, 2023). "A high level of TMEM97, as detected by three out of the four probes, was significantly associated with a low relapse-free survival (RFS) in all types of breast cancers." (PMID 38067394, 2023). "In the database with tumor microarray data (Kaplan–Meier Plotter), breast cancer patients with high levels of TMEM97 mRNA had a significantly reduced overall survival as revealed by three out of four probes mapped to TMEM97." (PMID 38067394, 2023). "Further, TMEM97 increases the resistance of breast cancer cells to tamoxifen through elaborating the mTOR/S6K1 signaling." (PMID 38067394, 2023). "To further assess the clinical relevance of the TMEM97/σ2 receptor in breast cancer, we queried TMEM97 using a public database, Kaplan–Meier plotter." (PMID 38067394, 2023). "Increased expression of TMEM97 in breast cancer cells stimulates estrogen receptor activities and growth." (PMID 38067394, 2023). "The results showed that the expression of TMEM97 protein was upregulated in breast cancer cell lines compared to normal mammary epithelial cells." (PMID 34615853, 2021). "We further demonstrated that TMEM97-mediated Wnt signaling plays an important role in the tumorigenesis of breast cancer." (PMID 34615853, 2021). "In breast cancer cells, knockout of TMEM97 attenuated the Wnt/β-catenin signaling cascade via regulating LRP6 phosphorylation, leading to a decrease in the expression of Wnt target genes AXIN2, LEF1, and survivin." (PMID 34615853, 2021). "We next investigated the effect of TMEM97 knockout on the biological behaviors of breast cancer cells (Hs578T and MDA-MB-231)." (PMID 34615853, 2021). "We checked the expression of TMEM97 in six breast cancer cell lines (SW527, BT549, MDA-MB-231, MDA-MB-468, MCF7, and Hs578T) and one normal mammary epithelial cell line (Hs578Bst) by Western blot." (PMID 34615853, 2021). "Examples of this were σ1 expression in ovarian and breast cancer, PGRMC1 expression in lung and breast cancer, and σ2/TMEM97 in melanoma and breast cancer cell lines." (PMID 33466391, 2021). "Knockout of TMEM97 abrogated its oncogenic properties through downregulating LRP6-mediated Wnt signaling in breast cancer." (PMID 34615853, 2021). "Since Wnt/β-catenin signaling has been implicated in stem cell-like properties in breast cancer, we examined the effect of TMEM97 knockout on the stemness of breast cancer cells." (PMID 34615853, 2021). "Breast cancer cells with TMEM97 knockout displayed a notable decrease in cell viability and proliferation compared with parental Hs578T and MDA-MB-231 cells." (PMID 34615853, 2021). "Our results demonstrated that TMEM97 displayed oncogenic effects through regulation of LRP6-mediated Wnt signaling in breast cancer." (PMID 34615853, 2021). "The involvement of TMEM97 in cholesterol homeostasis is consistent with the findings that TMEM97 is upregulated in proliferating versus quiescent breast cancer cells and TMEM97 is differentially expressed in normal and cancer tissues." (PMID 32668577, 2020). "Altogether, these results reveal a relevant functional role σ2R/TMEM97 on triple negative MDA-MB-231 breast cancer cells which agrees with previous results obtained in other cell models, as well as with different σ2R/TMEM97 agonists." (PMID 31973006, 2020).
breast cancer (continued). "It is also reported that transient knockdown of TMEM97 by siRNA decreased cell viability and migration/invasion in breast cancer, gastric cancer and glioma cell." (PMID 32668577, 2020). "Another study in breast cancer revealed that 59.7% of tumor samples displayed a higher expression level of TMEM97 compared to healthy tissue and that this overexpression correlated with larger tumor size and tumor recurrences." (PMID 30574087, 2018). "Moreover, it is important to note that while TMEM97 has been shown to be an oncogene in colon, gastric, and breast cancers, evidence also exists for its potential tumor-suppressor role in pancreatic and prostate cancers." (PMID 39995975, 2025). "Supporting this, a clinical trial correlated 18F-ISO-1 uptake in vivo with Ki-67 in ER+ breast cancer, notably the same IHC subset in which the correlation between σ2R/TMEM97 and proliferation is the strongest and the same subset in which the association with early relapse is the highest." (PMID 39804138, 2025). "Similarly, TMEM97 silencing in breast cancer cell lines MCF-7 and MDA-MB-231 elevated E-cadherin protein levels but reduced N-cadherin and vimentin along with other classic EMT markers such as ZEB1, Twist, Snail, and Slug." (PMID 39995975, 2025). "Breast cancer cells with increased expression of TMEM97 had a growth advantage over the control cells under both nutrition-limiting and sufficient conditions, while the knockdown of TMEM97 expression reduced tumor cell proliferations." (PMID 38067394, 2023). "The results suggest that TMEM97 could promote cell growth and proliferation even under estrogen-depleted conditions for ER-positive breast cancer cells." (PMID 38067394, 2023). "We found that TMEM97 could promote MCF7 breast cancer cell proliferation especially under nutrition-limited or estrogen-depleted conditions when compared with the vector control cells." (PMID 38067394, 2023). "Depletion of TMEM97 expression reduces estrogen receptor activities and breast cancer cell growth." (PMID 38067394, 2023). "Moreover, even though the expression of these receptors was diverse, the breast cancer cell line MCF7 expressed high levels (as compared to the majority of the rest of the cancer cell lines tested herein) of both σ2/TMEM97 and PGRMC1 receptors." (PMID 33466391, 2021). "Taken together, these results indicate that TMEM97 could promote the LRP6-mediated Wnt signaling pathway via regulating LRP6 phosphorylation in breast cancer cells." (PMID 34615853, 2021). "Moreover, an anti-CK1δ antibody pulled down endogenous LRP6 and TMEM97 in unmanipulated breast cancer MDA-MB-231 cells, demonstrating the existence of TMEM97–LRP6-CK1 complex." (PMID 34615853, 2021). "Collectively, our results suggest that TMEM97 may play an important role in cell viability, proliferation, colony formation, migration, and invasion in breast cancer cells." (PMID 34615853, 2021). "Importantly, TMEM97 knockout suppressed tumor growth through downregulating the Wnt/β-catenin signaling pathway in a breast cancer xenograft model." (PMID 34615853, 2021). "The data suggest that TMEM97 may be related to BRCA1 function in breast cancer cells." (PMID 32668577, 2020). "With TMEM97 identified as σ2R, we first determined the expression pattern of TMEM97 in human breast cancer tissues via immunohistochemical staining (IHC) with a validated TMEM97 antibody." (PMID 38067394, 2023).
breast cancer (continued). "For example, whereas anti-cancer properties have been traditionally attributed to putative S2R agonists, tumor growth was suppressed by TMEM97/S2R knockout in a breast cancer xenograft model." (PMID 36553653, 2022). "Knockdown of TMEM97 efficiently inhibited the invasion and EMT in breast cancer cells, accompanying with the reduction of Akt phosphorylation, β-catenin, survivin, and cyclin D1 expressions." (PMID 34615853, 2021). "[18F]ISO-1, which targets TMEM97, has been validated as a PET imaging biomarker of proliferative status in human breast cancer patients." (PMID 32668577, 2020). "In line with our observations, σ2R/TMEM97 was shown to be overexpressed in different cancer types, and even in patients with breast cancer." (PMID 31973006, 2020). "Based on the association of TMEM97 expression with estrogen receptors and the increased proliferation of ER-positive breast cancer MCF7 cells, we determined whether TMEM97 regulates ER transcriptional activity." (PMID 38067394, 2023). "The involvement of TMEM97/σ2R in the internalization and trafficking of cholesterol via LDL is consistent with our previous characterization of the σ2R is upregulated in proliferating versus quiescent breast cancer cells." (PMID 30443021, 2018). "All these studies demonstrated that TMEM97 expression could affect the prognosis of NSCLC, SQCLC, ovarian and breast cancer patients." (PMID 30574087, 2018). "We characterize five genes (TMEM97, IFT20, TNFAIP1, POLDIP2 and TMEM199) organized in a CSAGA on 17q11.2 (we term this the TNFAIP1/POLDIP2 CSAGA) and demonstrate their strong and reproducible co-regulatory transcription pattern in breast cancer tumours." (PMID 20158880, 2010). "Regarding the role of σR/TMEM97 in breast cancer, it has been recently described that the protein family involved in DNA damage, Poly (ADP-ribose) polymerase, and σR/TMEM97 might share the same signaling pathway in order to impair breast cancer cell proliferation." (PMID 31973006, 2020). "Similarly, for early breast cancer, the best three k-gene discriminators are {GPR109B, PCOLCE2, PCSK5}, {PCSK5+COL10A1, FERMT2+SPINT2, MAOA+IGJ}, {COL1A1+PCSK5+TF, GPX3+COL1A1+SPINT2, GPX3+FAP+TMEM97}, and {RRM2+COL1A1+GPR109B+IGJ, RRM2+COL1A1+GPR109B+IGJ, RRM2+COL1A1+GPR109B+SPINT2}, respectively." (PMID 21060876, 2010). "Also, significant differences in gene expression levels were observed for TMEM97 and POLDIP2 in different grades of breast cancer in both cohorts (not shown)." (PMID 20158880, 2010).